CX3CR1 (C-X3-C motif chemokine receptor 1)
Diseases named in the same sentence as CX3CR1 in open-access papers (continued):
Sharing a sentence is not in itself a finding about the gene and the disease.
cancer (continued). "Such frequencies were still significantly lower than CD8+ T cell frequencies in non-cancer controls suggesting that the fractalkine:CX3CR1 axis might be perturbed by malignancy in this study cohort." (PMID 30150990, 2018). "At present, resveratrol could delay and attenuate cancer-induced pain facilitation through intrathecal administration, and resveratrol could also attenuate cancer pain induced CX3CR1 upregulation and glial activation in the spine." (PMID 30584449, 2018). "Based on these studies and our observation, it is plausible to hypothesize that the endothelial cells lining the bone marrow sinusoids express membrane-associated CX3CL1, which can provide viable docking sites for circulating CX3CR1-expressing cancer cells." (PMID 28122354, 2017). "Therefore, a possible concentration gradient of this chemokine is formed, which is able to chemo-attract CX3CR1-bearing cancer cells from the blood circulation into the spine." (PMID 28122354, 2017). "These included genes involved in cell death and survival processes (BCLAF1, CFLAR, CASP1, and XIAP), genes associated with proliferation-driving transcription or cancer (KLF4, LEF1, SOX4, ID3), and genes associated with inflammation (CD28, CCR7, CX3CR1 and IFNG)." (PMID 28407008, 2017). "Therefore, higher concentration of CX3CL1 in bone marrow and serum are required to recruit cancer cells with low CX3CR1 expression." (PMID 28122354, 2017). "Our results revealed that PI3K/Akt may be a crucial signal regulator mediating fractalkine/CX3CR1 signal transduction in various cancers." (PMID 28903329, 2017). "The role of the CX3CL1/CX3CR1 axis in cancer pathogenesis has long been discussed." (PMID 24799766, 2014). "Third, CX3CR1 and its ligand help control the migration and recruitment of immune effector cells in numerous inflammatory diseases and may play a role in cancer progression, immune evasion, and metastasis." (PMID 24245985, 2013). "Furthermore, studies with fractalkine-null transgenic mice indicate that the ablation of the adhesive and chemotactic ligand of CX3CR1 dramatically impairs the skeletal dissemination of circulating cancer cells." (PMID 21933397, 2011). "Moreover, identifying the cancer types and patient subgroups that would benefit most from CX3CR1-engineered CAR-T cells, developing reliable biomarkers, and optimizing combination strategies with IL-15 or immune checkpoint inhibitors remain key areas for future investigation." (PMID 40508161, 2025). "However, the CX3CL1:CX3CR1 axis presents either pro- or antitumor effects in different cancers." (PMID 35140706, 2021). "Therefore, it remains elusive whether the CX3CR1 score would be useful in patients with other types of cancer." (PMID 33658501, 2021). "In addition, it has been demonstrated that CX3CL1/CX3CR1 signaling activity in spinal microglia is an essential process for development and maintenance of inflammatory pain, neuropathic pain and cancer pain." (PMID 25768734, 2015). "Increased expression of CX3CL1 recruits the CX3CR1‐positive macrophages to liver PMN, resulting in the upregulation of MMP9, which facilitated the migration of immune cells and cancer cells." (PMID 40032646, 2025). "CX3CR1 is a high-affinity chemokine receptor of CX3CL1 that is expressed in immune cells such as T cells, NK cells, and macrophages, as well as in some cancer cells." (PMID 38775151, 2024). "The correlation of CX3CR1 with Pan-cancer survival was calculated in GEPIA database, the OS and DFS analysis including 33 cancer types." (PMID 38241595, 2024). "Upregulated DEGs included chemokines and receptors (CCL2, CCL3L1, CCL4L2, and CX3CR1), known for their roles in recruiting myeloid-derived suppressor cells (MDSC) and prompting metastasis in certain cancer types." (PMID 38903524, 2024). "To assess the potential relevance of our findings in humans, we performed pan-cancer analyses of CX3CL1 and CX3CR1." (PMID 38618956, 2024).
cancer (continued). "NF-kB mediates cancer development and progression, and we found that NF-kB mRNA was upregulated upon CX3CL1 addition indicating a relationship between CX3CR1 activation and NF-kB signaling." (PMID 37771579, 2023). "Cell-cell interaction analysis showed that the CX3CL1-CX3CR1 pair was significantly enriched between Mono_CX3CR1 cells and cancer cells from MPR patients, indicating that CX3CL1 expression in cancer cells attract Mono_CX3CR1 monocytes in MPR patients." (PMID 36869384, 2023). "The DC_CD1C cells expressed CX3CR1, and the CX3CL1-CX3CR1 interaction was significantly enriched between DC_CD1C cells and cancer cells from MPR patients." (PMID 36869384, 2023). "Recently some research found one such chemokine that plays a critical role in the anti-cancer procession is CX3C chemokine ligand 1 (CX3CL1) and its receptor CX3C chemokine receptor 1 (CX3CR1)." (PMID 35734169, 2022). "The ligand of CX3CR1, CX3CL1 (or fractalkine), is expressed on DCs and endothelial and cancer cells." (PMID 36429101, 2022). "Firstly, by cell to cell contact through CD47 (cancer cell) and SIRPα (macrophage) binding, CCR2, or CX3CR1 chemokine receptors; Secondly, through soluble factors or exosomes loaded in IL-10." (PMID 32477352, 2020). "The findings made with these cells also supported by the results for clinical samples, in which CX3CR1 and HIF-1α levels are elevated as cancers progress." (PMID 31077234, 2019). "In both cancer and inflammation processes, CX3CL1 has been shown to stimulate chemotaxis, recruiting cells that expressed CX3CR1, such as natural killer (NK) cells, dendritic cells (DCs), and monocytes." (PMID 30845779, 2019). "The low affinity Fc gamma receptor (FCGR2A/CD32), the cytokine receptor CX3CR1 and IL11RA were also higher in cancers with RD." (PMID 30967156, 2019). "Understanding how TGF-β1 impairs the expression of CX3CR1 in CD56dim NK has potential clinical implications, since it could improve the current knowledge of the mechanisms that regulate the immune responses and, in cancer, participate in the escape from immune surveillance." (PMID 28791023, 2017). "Importantly, we demonstrated that HIF-1α may regulate cancer cell migration through CX3CR1." (PMID 22952674, 2012). "Importantly, several biomarkers (such as CX3CR1 and S100A4) were identified and verified to distinguish between responders and non‐responders to immunotherapy in both cancer mouse models and patients with cancer." (PMID 40574416, 2025). "Furthermore, in most cancers, MHS were positively correlated with the expression of chemokine receptor genes such as CX3CR1 and CCR9 and negatively correlated with CXCR5 (P < 0.05)." (PMID 41174507, 2025). "Limiting treatment only to the FKN/CX3CR1 signaling pathway will not be fully effective due to the numerous processes involved in tumors, which result in cancer immune evasion." (PMID 38731899, 2024). "Overall, the uncontrolled proliferation and apoptosis resistance of cancer cells do not necessarily depend directly on CX3CR1 but rather on EFGR signaling." (PMID 38731899, 2024). "The CX3CR1 is a specific receptor for CX3CL1 and is involved in CX3CL1‐mediated cancer progress." (PMID 37082943, 2023). "Like CXCL6, CX3CL1 can be cleaved and released by disintegrin or metalloproteinases but also by cathepsin S. Depending on the context, the expression of CX3CR1 and/or CX3CL1, in a wide number of cell types, may lead to opposite effects on cancer progression." (PMID 36429101, 2022). "It is noteworthy in this respect, that the genes showing the strongest signals of negative selection include several plasma membrane receptor proteins (e.g. ACKR3, CCR2, CCR5, CX3CR1, TBXA2R) that cancer cells utilize to promote migration, invasion, and metastasis." (PMID 33427197, 2021).
cancer (continued). "Relevantly, clinical samples exhibited a negative correlation between miR-561-5p expression and levels of CX3CL1 and CX3CR1+ in NK cells, cells that exhibit a relevant antitumor response 38, suggesting that CX3CL1 could have clinical relevance in cancer." (PMID 33391453, 2021). "Upon cancer cell injection, non-classical monocytes interact with cancer cells in a CX3CR1-dependent manner, infiltrate the lung, engulf cancer cell material, and promote NK cell recruitment." (PMID 33783686, 2021). "This work focuses on the ‘hallmarks of cancer’ involving CX3CL1 and its receptor CX3CR1." (PMID 32466280, 2020). "Role of CX3CR1/CX3CL1 axis in primary and secondary involvement of the nervous system by cancer." (PMID 33014792, 2020). "Furthermore, Ly6Clo monocytes drive immunosuppression and confer resistance to anti-VEGFR2 cancer therapy for CRC, and CX3CR1 is critical for Ly6Clo monocyte transmigration across the endothelium in murine CRC tumors." (PMID 31395078, 2019). "Notably, TNFAIP8L3, CCL14, CX3CR1, CCL21, IL1R1, and IL33 had higher expression levels in the lower-TMB subtype of at least 13 cancer types, while had higher expression levels in the higher-TMB subtype of at most 2 cancer types." (PMID 30634925, 2019). "Because our samples from the spine have grown for a relatively long time, it is not so surprising that these cancer cells fall within the classification of epithelial cancer cells, and were lacking in CX3CR1." (PMID 28122354, 2017). "Moreover, Erreni and colleagues demonstrated that glioblastoma cancer stem cells and progenitor cells express both CX3CL1 and CX3CR1, indicating that this axis operates early in tumorigenesis process." (PMID 24799766, 2014). "Therefore, several selected markers such as CX3CR1, A100A4, KLRG1, S1PR5, and S100A8 were investigated in cancer mouse models and patients with lung cancer to verify the feasibility of utilizing these markers to identify non‐responders and predict immunotherapy efficacy." (PMID 40574416, 2025). "In addition to the C3, for these genes (CXCL8, CX3CR1, GRM8, HTR1B, HTR1D, PTGER3, SSTR1 and SUCNR1) were related to survival in the ACC and it was also could be useful in other cancers 24-31." (PMID 34220331, 2021). "The interactions between cancer cells and non-classical monocytes and subsequent cancer cell material engulfment by non-classical monocytes depend on CX3CR1 expression in non-classical monocytes since these processes are decreased in CX3CR1 KO mice." (PMID 33783686, 2021). "For this reason, cancer cells no longer adhere to each other via CX3CR1." (PMID 32466280, 2020). "In addition, another possible explanation is that cancer cells with lack or low levels of expression of CX3CR1 are more like to spread to metastatic sites rather than stay in primary site." (PMID 28122354, 2017). "LRS does not stimulate accumulation of CX3CR1+ SPM-like cells, omental neoangiogenesis or implantation of cancer cells." (PMID 37345662, 2023). "For example, not all clusters were uniformly decreased in cancer, with a population of TBET- memory CD4 T cells (P1_28) and CD14- CX3CR1 + monocytes (P2_25) being elevated in cancer." (PMID 36307410, 2022). "An apparent trend towards lower chemokine receptor expression by T lymphocytes from carcinoma tissue was observed for the receptors CCR3 and CX3CR1, whereas CXCR5 was not expressed at all by T lymphocytes from carcinoma tissue." (PMID 29020986, 2017). "Of these, CX3CR1, which codes for the CX3C chemokine receptor 1, exhibited the strongest positive correlation with pSTAT3(Y705) (rho = 0.36), though CX3CR1 is not included in the COSMIC Cancer Gene Census." (PMID 27855189, 2016).
neurodegenerative disease (46 papers, 2011 to 2025). A disorder of the central nervous system characterized by gradual and progressive loss of neural tissue and neurologic function. "There is an urgent need to develop and validate new PET tracers targeting microglial CX3CR1 in the CNS, further offering new opportunities for the diagnosis and treatment of neuroinflammation-associated neurodegenerative diseases." (PMID 41424797, 2025). "Conversely, activation of CX3CL1/CX3CR1 axis can promote neural protection not only in different inflammatory conditions but also in pathological processes leading to neurodegenerative diseases and their associated inflammation." (PMID 37818457, 2023). "Single-cell RNA sequencing (scRNA-seq) studies have suggested that downregulation of Cx3cr1 in plaque-associated microglia is a primary event in the neuroinflammatory cascade in neurodegenerative diseases." (PMID 35764973, 2022). "Microglia in the uninflamed brain exhibit a homeostatic genetic signature, expressing mRNAs for P2ry12, Cx3cr1, Temem119, Siglech, Hexb, and Fcrls, which are all downregulated during aging and in neurodegenerative diseases associated with cognitive disruption." (PMID 36153630, 2022). "The expression of microglial signature genes, including TMEM119, P2RY12, and CX3CR1, is gradually reduced with age or in neurodegenerative diseases, suggesting the loss of homeostatic microglial function." (PMID 34920745, 2021). "Studies have shown a causal link between human CX3CR1 SNPs and increased susceptibility to various neurodegenerative diseases." (PMID 34408629, 2021). "SSC changes were consistent with CNS-myeloid cell morphological alterations observed in the hippocampus, and reduced CX3CR1 expression is related to the activated “damage associated microglia” (DAM) phenotype seen in neurodegenerative diseases." (PMID 34526998, 2021). "The neurotoxicity induced by activated microglia in neurodegenerative diseases seems to be worsened in CX3CR1-deficient mice, suggesting that the signaling through CX3CL1/CX3CR1 regulates the phenotype of microglia." (PMID 28690540, 2017). "Signaling through its receptor Cx3cr1 has been implicated in multiple neurodegenerative diseases, but the effects on neuronal pathology are variable." (PMID 27932942, 2016). "In addition, the receptor is also associated with inflammation, neurodegenerative diseases, and aging, and the CX3CR1 inhibitor KAND567 is under clinical trials for hyperinflammatory conditions (EudraCT: 2020-002322-85)." (PMID 33810010, 2021). "Moreover, Nurr1 deficiency resulted in a significant proportion of DAM-like phenotype microglia, which is a recently identified subpopulation characteristically associated with neurodegenerative diseases, as determined by the changes of Cx3cr1, Itgax, Trem2, and Tmem119." (PMID 37990334, 2023). "As a result, the specific role of microglial CX3CR1 in neurodegenerative diseases remains controversial and warrants further investigation." (PMID 41424797, 2025). "Recent years have seen an increase in studies exploring the roles of CX3CL1/CX3CR1 signaling in aging-related neurodegenerative diseases, including AD and PD." (PMID 40822679, 2025). "CX3CL1/CX3CR1 signaling has been well established as a contributor to aging-related neurodegenerative diseases." (PMID 40822679, 2025). "Both mFKN and sFKN pose unique effects signaling through microglial CX3CR1 in many neurodegenerative diseases and several studies support the contribution of the CX3CR1/FKN signaling axis in DR, but their biological activities in DR are still being elucidated." (PMID 38311721, 2024). "For example, CX3CR1−/− mice achieved improved cognitive function by persistently maintaining hippocampal neurogenesis in aging and neurodegenerative diseases." (PMID 38421089, 2024). "Of these, fractalkine and signaling via the fractalkine receptor CX3CR1 have been proposed as a promising target for treatment of neurodegenerative disease, including AD." (PMID 38093257, 2023).
neurodegenerative disease (continued). "Our present review summarizes the current data related to the role of the CX3CL1/CX3CR1 signaling pathways in animal models of selected neurodegenerative diseases and their potential use in the clinic." (PMID 33065974, 2020). "In neurodegenerative disease models, CX3CR1 depletion was reported to sustain microglial inflammatory responses and degrade synaptic circuits, thus promoting neurodegeneration." (PMID 28388927, 2017). "Another surface receptor, the CX3C chemokine fractalkine receptor CX3CR1, is almost exclusively expressed in microglia throughout the CNS, which is involved in progression of neurodegenerative disease by altering microglial activities." (PMID 22666624, 2012). "Deletion of CX3CR1 expression in microglia results in progressive neuronal cell death in an animal model of neurodegenerative disease, by inducing microglial dysfunction." (PMID 22666624, 2012). "Given that aging is a common risk factor for neurodegenerative diseases, investigating the roles of CX3CL1/CX3CR1 signaling during natural aging could enhance our understanding of their implications in aging-related conditions." (PMID 40822679, 2025). "Any disruptions in the CX3CL1/CX3CR1 signaling pathway may result in the development of neurodegenerative diseases." (PMID 39766878, 2024). "CX3CR1 and nonclassical monocytes in particular will be a focus of future work exploring the role of these peripheral signals in additional tau-associated neurodegenerative diseases." (PMID 37464408, 2023). "The CX3CL1– CX3CR1 axis may play an important role in immunoregulation in several neurodegenerative diseases such as PD, AD and ALS." (PMID 24069165, 2013). "CX3CL1 and CX3CR1 are normally expressed at relatively high levels in the brain but decrease during aging, and may be involved in neurodegenerative diseases." (PMID 23028885, 2012). "However, more work is also necessary to determine the role of CX3CL1 and CX3CR1 in normal physiological conditions, as well as, in models of neurodegenerative diseases." (PMID 21266082, 2011). "The complementary expression of fractalkine on neurons and CX3CR1 on microglia establishes a unique communication whereby neurons constitutively express and release fractalkine to regulate the function of microglia in various models of central neurodegenerative diseases." (PMID 22536384, 2012). "In this study, CuO-NPs caused CX3CR1 signal dysregulation in BV2 microglia, with a concentration-dependent decrease, which confirms that CuO-NPs may cause neuronal damage by triggering the imbalance of microglia homeostasis and promoting neurodegenerative disease occurrence." (PMID 40278547, 2025). "Our results are in line with the literature documenting the interaction between reactive Cx3cr1+ cells and CD4+ T cells in various neurodegenerative disease models." (PMID 37689689, 2023). "CX3CR1+/GFP mice have been widely used in studying microglia dynamics and activation in various models of neurodegenerative diseases." (PMID 36092814, 2022). "Of particular interest in recent studies of neurodegenerative disease is the role of the chemokine fractalkine (CX3CL1, FKN) and its cognate receptor (CX3CR1)." (PMID 34408629, 2021).